FAM225A (family with sequence similarity 225 member A)
Synonyms: DKFZp686A0127; C9orf109; LINC00256A; NCRNA00256A
Gene: Long non-coding RNA gene on chromosome 9 (113,111,624 to 113,119,928, forward strand). Ensembl gene ENSG00000231528.
Diseases named in the same sentence as FAM225A in open-access papers:
FAM225A is named in the same sentence as 11 diseases in open-access papers, as found by Europe PMC text mining. Sharing a sentence is not in itself a finding about the gene and the disease. The quoted sentences say what the papers report.
nasopharyngeal carcinoma (26 papers, 2019 to 2025). A carcinoma arising from the nasopharyngeal epithelium. "For example, the lncRNA FAM225A promotes nasopharyngeal carcinoma (NPC) tumorigenesis and metastasis by acting as a ceRNA to sponge miR-590-3p and miR-1275, thereby upregulating ITGB3140." (PMID 39218979, 2024). "For example, the stability of LncRNA FAM225A is strengthened by m6A modification, which mediated by METTL3, thus up-regulating LncRNA FAM225A level in nasopharyngeal carcinoma cells." (PMID 37365581, 2023). "LncRNA FAM225A is upregulated in nasopharyngeal carcinoma (NPC), and its overexpression promotes NPC tumorigenesis and metastasis." (PMID 35287542, 2022). "FAM225A was found to be up-regulated in some tumors such as nasopharyngeal carcinoma and gastric cancer and to promote tumorigenesis and development via sponging miRNAs." (PMID 35967341, 2022). "In nasopharyngeal carcinoma, lncRNA FAM225A acts as a ceRNA, sequestering miR-590-3p and miR-1275, thus activating FAK/PI3K/Akt signaling; in this scenario, m6A modification contributes to this mechanism by increasing the lncRNA FAM225A stability." (PMID 34282776, 2021). "The lncRNA FAM225A is overexpressed in nasopharyngeal carcinoma, and m6A modification is identified on FAM225A enhancing its RNA stability." (PMID 33754077, 2021). "FAM225A was found to be one of the most highly expressed lncRNAs in nasopharyngeal carcinoma by a microarray analysis." (PMID 33245102, 2020). "FAM225A was a newly identified lncRNA and functioned as an oncogene that promoted nasopharyngeal carcinoma cell viability and invasion by trapping miR-590-3p and miR-1275, indicating a functional role in tumorigenesis and metastasis." (PMID 33245102, 2020). "For example, lncRNA FAM225A facilitates nasopharyngeal carcinoma (NPC) tumor formation and metastasis by sponging miR-590-3p/miR-1275 as a ceRNA and increasing ITGB3 expression." (PMID 33614632, 2020). "FAM225A is a new lncRNA and has only been explored in nasopharyngeal carcinoma to accelerate tumorigenesis." (PMID 33006432, 2020). "FAM225A, a novel lncRNA, has only been proved to accelerate the tumorigenesis and metastasis in nasopharyngeal carcinoma by serving as a ceRNA to interact with miR‐590‐3p/miR‐1275 and increasing TGB3 expression." (PMID 33006432, 2020). "FAM225A was proved to influence cell progression and forecast unfavorable prognosis in nasopharyngeal carcinoma." (PMID 32343052, 2020). "Other sponges may contribute to tumorigenesis and metastasis, such as FAM225A in nasopharyngeal carcinoma (NPC)." (PMID 40501482, 2025). "LncRNA FAM225A is highly m6A enriched, leading to its stabilization in nasopharyngeal carcinoma." (PMID 37986103, 2023). "LncRNA FAM225A could expedite cell migration of nasopharyngeal carcinoma through playing as a ceRNA to regulate miR-590-3p/miR-1275/ITGB3 axis." (PMID 35761386, 2022). "FAM225A is a novel lncRNA, only has been explored in nasopharyngeal carcinoma tumorigenesis." (PMID 33006432, 2020). "m6A modification has been shown to regulate lncRNA stability by mediating ceRNA models, like FAM225A, an lncRNA that significantly connects to the proliferative, migrative, and invasion capacities of nasopharyngeal carcinoma (NPC) cells." (PMID 38102645, 2023). "LncRNA FAM225A was proved to enhance cell proliferation, migration, invasion, and tumor growth in nasopharyngeal carcinoma (NPC)." (PMID 32343052, 2020). "Similarly, FAM225A exerts a ceRNA effect and competes for binding to miR‐590‐3p and miR‐1275, thereby reducing their inhibitory effect on ITGβ3 and promoting proliferation and invasion of nasopharyngeal carcinoma cells." (PMID 32368853, 2020). "METTL3 has also been shown to increase the stability of FAM225A, a lncRNA overexpressed in nasopharyngeal carcinoma (NPC), to promote tumorigenesis." (PMID 32911345, 2020). "In nasopharyngeal carcinoma (NPC), the m6A level of oncogenic lncRNA FAM225A is elevated, resulting in enhanced stability and higher expression of FAM225A." (PMID 31801551, 2019).
nasopharyngeal carcinoma (continued). "In nasopharyngeal carcinoma (NPC), the oncogenic lncRNA FAM225A stabilized by m6A modifications serve as a sponge for miR-590-3p and miR-1275, activating the FAK/PI3K/Akt signaling pathway and promoting tumorigenesis and metastasis." (PMID 36866275, 2023). "LncRNA FAM225A was upregulated in nasopharyngeal carcinoma (NPC) tumor tissue, and high expression of FAM225A was related with poor clinical prognosis." (PMID 36230970, 2022). "lncRNA FAM225A has been shown to act as a ceRNA absorbing miR-1275, up-regulating ITGB3 and promoting metastasis in nasopharyngeal carcinoma." (PMID 34118875, 2021).
esophageal squamous cell carcinoma (5 papers, 2020 to 2024). Esophageal squamous cell carcinoma (ESCC) is a type of esophageal carcinoma (EC) that can affect any part of the esophagus, but is usually located in the upper or middle third. "rs59657211 at the FAM225A locus has been reported to be involved in the tumorigenesis and metastasis of several types of cancers, including nasopharyngeal, colorectal, and esophageal squamous cell cancer." (PMID 38263039, 2024). "Exosome-derived FAM225A has been suggested to be a therapeutic target for esophageal squamous cell carcinoma (ESCC) patients." (PMID 36338993, 2022). "This study aims to investigate the regulatory mechanism of FAM225A in esophageal squamous cell carcinoma (ESCC)." (PMID 33006432, 2020).
colorectal cancer (3 papers, 2020 to 2022). A primary or metastatic malignant neoplasm that affects the colon or rectum. "In another study, FAM225A was overexpressed in colorectal cancer tissues and cell lines and predicted unfavorable outcome of colorectal cancer patients." (PMID 33442405, 2021). "Besides, FAM225A was found to facilitate colorectal cancer progression by sponging miR-613." (PMID 35017465, 2022). "FAM225A could also regulate NOTCH3 expression and sponge miR-613 expression to enhance the colorectal cancer development." (PMID 33442405, 2021).
autoimmune disease (1 paper, 2025). A disorder resulting from loss of function or tissue destruction of an organ or multiple organs, arising from humoral or cellular immune responses of the individual to their own tissue constituents. "To explore novel lncRNA biomarkers in patients with triple-SN MG, we searched the top five upregulated and downregulated lncRNAs in PubMed and found that lncRNA FAM225A was associated with autoimmune diseases and was not differentially expressed in antibody-positive patients with MG." (PMID 41488644, 2025).
hepatoma (1 paper, 2020). "Additionally, dysregulation of FAM225A and miR-130a-5p remarkably affected hepatoma cell sensitivity to sorafenib via targeting Cyclin G1 (CCNG1), which might provide us with more potential therapeutic strategies for chemosensitization of HCC cells to sorafenib." (PMID 33245102, 2020).
systemic lupus erythematosus (1 paper, 2025). An autoimmune multi-organ disease typically associated with vasculopathy and autoantibody production. "LncRNA FAM225A participated in systemic lupus erythematosus and some tumors via sponging miRNAs." (PMID 41488644, 2025).
tumor (12 papers, 2020 to 2024). "Subsequently, we discovered that higher FAM225A expression was positively associated with a more profound lymphatic metastasis rate, larger tumor size, and more advanced tumor stage." (PMID 35017465, 2022). "Meanwhile, the tumor metastasis model assay in vivo showed that lung metastasis in the FAM225A knockdown group was alleviated." (PMID 35017465, 2022). "The correlation between FAM225A levels and patient clinicopathological characteristics suggested that higher FAM225A expression tended to correlate with more profound lymphatic metastasis rate, larger tumor size, and more advanced tumor stages." (PMID 35017465, 2022). "Zheng’s found lncRNA FAM225A promoted nasopharyngeal carcinogenesis cell proliferation, migration, invasion, tumor growth and metastasis via FAK signaling pathway." (PMID 33587236, 2021). "NETO2 was determined as a target of miR-206 and miR-143-5p, and participation of NETO2 tumor progression and angiogenesis through overexpression of lncRNA FAM225A absorbed miR-206 was revealed." (PMID 33362854, 2020). "In order to verify the inhibitory effects of FAM225A on sorafenib sensitivity, we constructed a tumor xenograft model by subcutaneously injecting HepG2/SOR cells stably knockdown of FAM225A to nude mice." (PMID 33245102, 2020). "Clinicopathological analysis indicated that increased expression of FAM225A was associated with a higher lymph node metastasis rate, larger tumor size, and more advanced tumor stage, and the increased expression of FAM225A indicated poor prognosis in GC patients." (PMID 35017465, 2022). "The higher expression of FAM225A was discovered in tumor tissues than normal tissues." (PMID 32343052, 2020). "Moreover, the high expression of FAM225A was markedly correlated with tumor size, TNM stage, and lymph node status." (PMID 33006432, 2020). "The effects of FAM225A knockdown in xenograft tumor were verified by qRT-PCR analysis." (PMID 33245102, 2020). "In a word, FAM225A/miR‐613/NOTCH3 axis may play a tumor‐facilitator in CRC cell progression." (PMID 32343052, 2020). "In oesophageal squamous cell carcinoma, exosome lncRNA FAM225A upregulates the expression of NETO2 and FOXP1 by absorbing miR‐206, participating in progression and angiogenesis of tumor." (PMID 38652109, 2024). "Therefore, FAM225A/miR‐613/NOTCH3 axis may play a tumor‐facilitating role in CRC cell progression." (PMID 32343052, 2020). "In order to explore whether FAM225A was involved in HCC progression, we first measured the FAM225A expression in 30 human HCC samples and corresponding non-tumor controls using qRT-PCR assay." (PMID 33245102, 2020). "FAM225A could regulate ITGB3 expression by sponging miR-590-3p and miR-1275 and resulted in tumorigenesis and metastasis, indicating its oncogenic role in tumor development." (PMID 33245102, 2020). "Our results also revealed that FAM225A directly interacted with miR-130a-5p by luciferase reporter assay, and miR-130a-5p expression was obviously lower in HCC tissues and in sorafenib-resistant cells, confirming the role of miR-130a-5p acting as a tumor suppressor." (PMID 33245102, 2020).
cancer (5 papers, 2021 to 2024). A tumor composed of atypical neoplastic, often pleomorphic cells that invade other tissues. "Various lncRNAs such as LINC00857, MIR17HG, NKX2-1-AS1, LINC01234, and FAM225A have been found to manipulate specific miRNAs to influence cancer cell behavior." (PMID 39172101, 2024). "Therefore, exosomal FAM225A can be transferred to other cancer cells, inciting cell survival and EMT." (PMID 35055115, 2022). "Similarly, LNC942, lncRNA XIST and lncRNA FAM225A can affect cell proliferation and cancer progression under the m6A “writer”-mediated m6A modification." (PMID 35004679, 2021). "By FEELnc, we predicted that the long noncoding gene FAM225A, AL356417.2 and BHLHE40-AS1 can regulate mRNA by trans-regulation function or ceRNA which existing research focuses on cancer and immune disease." (PMID 37369992, 2023). "METTL3-mediated methylation can also enhance the stability of lncRNA FAM225A, which regulates the expression of ITGB3 by binding to miR-590-3p and miR-1275 as ceRNA, and thus activates the FAK/PI3K/AKT signalling pathway and promotes the invasion and migration of cancer cells." (PMID 35004679, 2021).
FAM225A also shares sentences with these, for which no sentence is quoted: gastric cancer (2 papers); immune disease (1); myasthenia gravis (1).